SPARCL1 (SPARC like 1)
Diseases named in the same sentence as SPARCL1 in open-access papers (continued):
Sharing a sentence is not in itself a finding about the gene and the disease.
dyslipidemia (2 papers, 2022 to 2025). "Specifically, each one standard deviation increase in SPARCL1 was associated with approximately 20% and 12% lower risks of hypertriglyceridemia and overall dyslipidemia, respectively." (PMID 40649979, 2025). "In the current study we observed linear association between serum Sparcl1 and triglycerides level as well as prevalence of dyslipidemia." (PMID 36387870, 2022). "The inverse associations between serum Sparcl1 and dyslipidemia were generally similar across all subgroups." (PMID 36387870, 2022). "Prospective studies are needed to further confirm the association of plasma Sparcl1 and dyslipidemia." (PMID 36387870, 2022). "Inverse associations between serum Sparcl1 and dyslipidemia were generally similar across subgroups (all P for interaction > 0.05)." (PMID 36387870, 2022). "Logistic regression analysis suggested that serum Sparcl1 was significantly associated with decreased risk of prevalent dyslipidemia (P for trend=0.011)." (PMID 36387870, 2022). "The association between serum Sparcl1 and dyslipidemia were generally consistent across subgroups (all P for interaction > 0.05)." (PMID 36387870, 2022). "In conclusion, our study found that serum Sparcl1 was inversely associated with the prevalence of dyslipidemia in a Chinese population, suggesting the potential role of Sparcl1 as a metabolic regulator." (PMID 36387870, 2022). "Serum Sparcl1 was significantly associated with decreased risk of prevalent dyslipidemia in Chinese population." (PMID 36387870, 2022). "This is the first study found that serum Sparcl1 was significantly associated with decreased prevalent risk of hypertriglyceridemia and dyslipidemia in Chinese adults, suggesting the importance of Sparcl1 in the metabolic regulation, especially lipid metabolism." (PMID 36387870, 2022). "However, significant linear association of Sparcl1 with the prevalence of dyslipidemia were observed (P for linearity = 0.011)." (PMID 36387870, 2022). "Per SD increment of Sparcl1 was associated with 20% (OR, 0.80; 95%CI, 0.69-0.94) lower prevalence of hypertriglyceridemia and 12% (OR, 0.88; 95%CI, 0.79-0.97) lower prevalence of dyslipidemia." (PMID 36387870, 2022). "Moreover, per SD increment of serum Sparcl1 was associated with 20% decreased prevalence of hypertriglyceridemia and 12% decreased prevalence of dyslipidemia." (PMID 36387870, 2022). "Therefore, our results on the association of Sparcl1 and dyslipidemia could exclude the influence of these comorbidities to some extent." (PMID 36387870, 2022). "However, evidence on the association of Sparcl1 with systematic metabolic profiles and dyslipidemia in human population is unknown." (PMID 36387870, 2022). "Epidemiological studies have shown that elevated serum SPARCL1 levels are associated with lower triglyceride levels, increased HDL-C, and a reduced risk of dyslipidemia." (PMID 40649979, 2025). "Multivariable-adjusted logistic regression analyses were performed to evaluate the relationship of serum Sparcl1 with prevalent dyslipidemia." (PMID 36387870, 2022). "Experimental and large clinical studies are also warranted to explore the specific role of Sparcl1 in the development of dyslipidemia." (PMID 36387870, 2022). "Odds ratios (95% confidence intervals) for prevalent dyslipidemia according to serum Sparcl1 levels." (PMID 36387870, 2022). "The potential protective role of Sparcl1 for dyslipidemia needs confirmation in other study populations." (PMID 36387870, 2022). "The prevalence of dyslipidemia was significantly decreased with increasing of the quartiles of serum Sparcl1 (P for trend = 0.0107)." (PMID 36387870, 2022). "Multivariable-adjusted restricted cubic spline analyses indicated that there was no non-linear association between serum Sparcl1 and the prevalence of dyslipidemia (P for non-linearity = 0.93)." (PMID 36387870, 2022).
dyslipidemia (continued). "For the individual components of dyslipidemia, similar trend was found in the association between serum Sparcl1 and increased TG (P for non-linearity=0.45, P for linearity = 0.0052)." (PMID 36387870, 2022). "However, population studies on the association of Sparcl1 and metabolic profile and dyslipidemia are lacking." (PMID 36387870, 2022). "Sparcl1 might be an alternative target of the treatment of hypertriglyceridemia and dyslipidemia." (PMID 36387870, 2022). "Thus, to reveal whether serum Sparcl1 is associated with metabolic phenotypes in human population, we systematically examined the levels of serum Sparcl1, metabolic measures, particularly, lipid profiles and dyslipidemia in a cross-sectional study among Chinese population." (PMID 36387870, 2022). "Participants with dyslipidemia have lower level of serum Sparcl1 than those without dyslipidemia (725.11 vs 657.86 ng/mL, P =0.006)." (PMID 36387870, 2022). "One possibility is that Sparcl1 might regulate the PPARγ signal pathway and LPL expression, thereby regulating lipid metabolism and the development of dyslipidemia." (PMID 36387870, 2022).
gastrointestinal stromal tumor (2 papers, 2021 to 2024). "SPARCL1 was downregulated in gastrointestinal stromal tumors, which contributed to cell migration and invasion, and SPARCL1 can predict the prognosis of gastrointestinal stromal tumors (P = 0.008)." (PMID 33980221, 2021).
Hepatic steatosis (2 papers, 2022 to 2024). Steatosis is a term used to denote lipid accumulation within hepatocytes. "Moreover, the upregulation of SPARCL1, by either using recombinant SPARCL1 injection or SPARCL1 overexpression, accelerated hepatic inflammation and liver injury in mice with liver steatosis." (PMID 35909571, 2022). "Therefore, inhibition of SPARCL1 could potentially alleviate chronic metabolic inflammation, and then attenuate hyperlipidemia and hepatic steatosis." (PMID 39055214, 2024).
influenza infection (2 papers, 2024 to 2025). "These experiments indicate that endothelial deficiency in Sparcl1 protects against severe influenza pneumonia, at least partially by attenuating local inflammation." (PMID 38762489, 2024). "RNA sequencing (RNA-seq) of isolated lung macrophages (CD45+Ly6G−CD64+F4/80+) on day 20 post-influenza infection was used to further examine the consequences of EC overexpression of Sparcl1." (PMID 38762489, 2024). "Here, we report that expression of Sparcl1, a secreted matricellular protein, is upregulated in pulmonary capillary endothelial cells (EC) during influenza-induced lung injury." (PMID 38762489, 2024). "We did not observe obvious changes in the number of macrophages during homeostasis after endothelial deletion of Sparcl1 but observed a reduction in total macrophages during influenza infection." (PMID 38762489, 2024). "Sparcl1 expression has been shown to increase in gCap cells upon influenza infection." (PMID 40118055, 2025). "Immunostaining showed that SPARCL1 was mainly expressed in capillary ECs (especially gCap ECs), as well as mesenchymal/stromal cells, and was significantly increased on day 20 after influenza injury." (PMID 38762489, 2024). "Additionally, although we have observed an association between circulating SPARCL1 and post-COVID recovery, the difficulty in obtaining sufficient numbers of samples from patients hospitalized with pure influenza pneumonia raises uncertainty about the role of SPARCL1 in the human influenza setting." (PMID 38762489, 2024). "Our ELISA data showed that SPARCL1 was significantly upregulated during pneumonia before gradually returning to normal levels during recovery, so we speculated that the high expression of SPARCL1 in influenza-induced lung injury was related to the level of local inflammation." (PMID 38762489, 2024). "The qPCR analysis on sorted lung ECs from uninjured mice confirmed the deletion of Sparcl1, and ELISA data further validated a significant reduction in SPARCL1 protein levels in BALF and lung tissue homogenate on day 12 after influenza infection." (PMID 38762489, 2024). "Having established that EC overexpression of Sparcl1 worsens viral pneumonia through TLR4 signaling, we next explored whether inhibition of TLR4 is sufficient to ameliorate influenza-induced injury in mice." (PMID 38762489, 2024).
ischemic stroke (2 papers, 2022 to 2025). A stroke disorder caused by obstruction of blood flow to the brain, due to thrombotic (local blood clot formation) or embolic (due to a blood clot or other material traveling from another site) event. "Methods: we examined the associations of SPARCL1 polymorphisms (rs1049544, rs1130643, rs7695558, rs1049539) with ischemic stroke." (PMID 41009953, 2025). "This study investigated SPARCL1 gene polymorphisms in ischemic stroke to identify potential biomarkers for brain injury treatment." (PMID 41009953, 2025). "Although this study confirmed a genetic association between ischemic stroke and SPARCL1, some limitations should be acknowledged." (PMID 41009953, 2025). "Haplotype analysis indicated that the SPARCL1 rs1049539 T, rs1049539 C, rs7695558 G, rs1049544 G, rs1049544 C, and rs1130643 C alleles were associated with increased ischemic stroke incidence." (PMID 41009953, 2025). "The SPARCL1 rs1049544 G>C genotype showed a significant association with ischemic stroke and was specifically linked to the LAD subtype." (PMID 41009953, 2025). "Subtype analyses identified associations between SPARCL1 polymorphisms and specific ischemic stroke subtypes." (PMID 41009953, 2025). "Interaction analysis was conducted to evaluate the potential synergistic effects between SPARCL1 polymorphisms and clinical risk factors on ischemic stroke prevalence." (PMID 41009953, 2025). "This study investigated the relationships of four SPARCL1 polymorphisms with ischemic stroke to explore their potential relevance as genetic risk factors." (PMID 41009953, 2025). "Given the central importance of astrocytic response and synaptic recovery in post-stroke repair, we hypothesized that genetic variants of SPARCL1 may be associated with the prevalence and prognosis of ischemic stroke." (PMID 41009953, 2025). "Here, we conducted a genetic epidemiological study on single nucleotide polymorphisms (SNPs; SPARCL1 rs1049539 T>C, rs7695558 A>G, rs1049544 G>C, rs1130643 T>C) to investigate associations of SPARCL1 with the prevalence and prognosis of ischemic stroke in the Korean population." (PMID 41009953, 2025). "Based on these findings, we propose that SPARCL1 polymorphisms influence the risk of ischemic stroke and may be useful as genetic markers for risk assessment." (PMID 41009953, 2025). "Importantly, the associations between SPARCL1 polymorphisms and ischemic stroke remained statistically significant after adjustment." (PMID 41009953, 2025). "Thus, further epidemiological research involving heterogeneous populations is essential to deepen understanding of the relationship between SPARCL1 polymorphisms and ischemic stroke prevalence." (PMID 41009953, 2025). "If future studies establish a definitive causal role for the SPARCL1 pathway in ischemic stroke, targeted prevention strategies may become feasible." (PMID 41009953, 2025). "In addition, Sparcl1 was also found to be independently associated with ischemic stroke severity in 132 patients with acute ischemic stroke." (PMID 36387870, 2022). "The SPARCL1–calcyon interaction may be particularly relevant in the context of ischemic stroke, given that early synaptic recovery is critical for functional restoration." (PMID 41009953, 2025). "In addition, Sparcl1 was also reported to be involved in the development of Alzheimer’s disease and ischemic stroke." (PMID 36387870, 2022). "Although SPARCL1 has not been extensively studied in the context of ischemic stroke, its biological functions and expression profiles in other neurological diseases suggest a potential relevance." (PMID 41009953, 2025).
Paralysis (2 papers, 2016 to 2025). Paralysis of voluntary muscles means loss of contraction due to interruption of one or more motor pathways from the brain to the muscle fibers. "SparcL1 was identified to be a biphasic DEG (FDR = 7.2 × 10–12 during paralysis, FDR = 0.0037 during recovery) and was found by SynGO in the extracellular matrix of synaptic cleft GO:0098965 term and synaptic membrane adhesion GO:0099560 term." (PMID 39848964, 2025). "In both remitting and non-remitting EAE models, SPARC-like 1/SPARC mRNA and protein ratios inversely correlated with clinical paralysis severity scores." (PMID 27581191, 2016).
pneumonia (2 papers, 2024). An acute, acute and chronic, or chronic inflammation focally or diffusely affecting the lung parenchyma, caused by an infection in one or both of the lungs (by bacteria, viruses, fungi, or mycoplasma.). "In addition, it was shown that mice with genetic ablation for SPARCL1 (ECSparcl1-KO) presented mild symptoms of pneumonia, less loss of bodyweight, and faster recovery with improving oxygen saturation compared with WT mice." (PMID 39273209, 2024). "Furthermore, SPARCL1 deficiency protects against pneumonia due to COVID19, as these mice were able to attenuate local inflammation." (PMID 39273209, 2024). "Our results thus implicate SPARCL1 as a potential prognosis biomarker for deadly COVID-19 pneumonia and as a therapeutic target for taming hyperinflammation in pneumonia." (PMID 38762489, 2024). "This further supports the previous conclusion that EC-derived SPARCL1 aggravates local lung inflammation in pneumonia, thus worsening lung injury." (PMID 38762489, 2024). "To further confirm that EC-derived SPARCL1 negatively contributes to pneumonia severity, we again targeted Sparcl1 cDNA to the ROSA26 locus, preceded by a loxP flanked “stop” sequence, in mouse ES cells." (PMID 38762489, 2024). "Instead of direct effects on the vasculature, our findings suggested that the high expression of SPARCL1 by ECs during pneumonia contributes to the worsening of lung injury by driving inflammation, ultimately causing more harm than benefit." (PMID 38762489, 2024). "Further, we show that antagonism of TLR4 can specifically rescue morbidity in SPARCL1 overexpressing mice, suggesting a potential therapeutic intervention for pneumonia patients with high levels of circulating SPARCL1." (PMID 38762489, 2024). "As such, we recognize that SPARCL1’s predictive and functional roles may differ between different etiologies of pneumonia." (PMID 38762489, 2024). "In agreement with results using ECSparcl1-OE mice, EC loss of Sparcl1 resulted in fewer M1_like but more M2_like macrophages during pneumonia, with no obvious changes under homeostasis." (PMID 38762489, 2024). "Integration of our findings in mouse models and patient samples leads us to suggest that assessing SPARCL1 levels in pneumonia patients serves not only as a biomarker of disease severity, but may allow for personalized medicine approaches." (PMID 38762489, 2024). "Our findings reveal that the vascular-derived molecule SPARCL1 is a critical paracrine signaling factor between capillary endothelial cells and macrophages and that macrophage responses to SPARCL1 contribute to the severity of pneumonia." (PMID 38762489, 2024). "Similarly, it was also shown that overexpression of SPARCL1 generated the opposite effects, worsening pneumonia in animals." (PMID 39273209, 2024).
Stroke (2 papers, 2025). Sudden impairment of blood flow to a part of the brain due to occlusion or rupture of an artery to the brain. "Further analysis of interactions between SPARCL1 polymorphisms and risk factors demonstrated a synergistic effect on stroke risk under the recessive model for rs1049544." (PMID 41009953, 2025). "Disruption of these processes, potentially influenced by genetic variation in SPARCL1, could impair post-ischemic recovery and increase susceptibility to stroke." (PMID 41009953, 2025). "These synapse-related functions of SPARCL1 may have implications for stroke risk, as efficient synaptic reconstruction and maintenance of neurovascular integrity are critical in mitigating the effects of ischemic injury." (PMID 41009953, 2025).
trachoma (2 papers, 2015 to 2020). "Matricellular proteins such as SPARCL1 and CTGF have received little attention in trachoma to date; it is plausible that they have an important role in the development of scar tissue." (PMID 25970613, 2015). "Nevertheless, IL23A, SPARCL1, and PDGFB may be key mediators driving pathological inflammation and fibrosis in trachoma, and molecules that inhibit their action could hold therapeutic potential in preventing scarring progression." (PMID 31964744, 2020).
atherosclerosis (1 paper, 2025). A disease characterized by the build-up of fatty material and calcium deposition in the arterial wall resulting in partial or complete occlusion of the arterial lumen. "The three most promising proteins (CELSR2, FN1, and SPARCL1) were identified as potential therapeutic targets for atherosclerosis, while APOE, LPA, APOA5, TGFB1, and AGER also hold potential as drug targets for the disease." (PMID 40649979, 2025). "CELSR2, FN1, SPARCL1, APOE, LPA, APOA5, and TGFB1 exhibit causal associations with both atherosclerosis and four cardiovascular diseases, suggesting their potential as therapeutic targets for atherosclerosis." (PMID 40649979, 2025). "Endothelial dysfunction is a critical initiating factor in atherosclerosis, and the role of SPARCL1 in stabilizing the vascular endothelium, along with its confirmed involvement in atherosclerosis development, suggests its potential as a therapeutic target for the disease." (PMID 40649979, 2025). "Notably, SPARCL1 expression has been confirmed in atherosclerotic tissues; however, whether it plays a protective or promotive role in atherosclerosis remains unclear." (PMID 40649979, 2025).
brain injuries (1 paper, 2012). "Sparcl1 is a secreted extracellular matrix (ECM) glycoprotein known to be involved in cell adhesion, migration, and ECM remodeling after brain injuries." (PMID 23209762, 2012).
breast tumor (1 paper, 2024). "In naive and breast tumor‐bearing immunocompetent mice, FTY720/Fingolimod that targets S1PR1, suppressed paclitaxel‐induced neuropathic pain, astrocyte activation, the astrocyte‐secreted synaptogenic protein Sparcl1/Hevin and synapse formation." (PMID 39126272, 2024).
cardiomyopathies (1 paper, 2024). "Furthermore, they compared the genes with consistent change across all three cardiomyopathies to the druggable genome, resulting in 39 druggable genes (10 up-regulated and 29 down-regulated) including CYD2J2, MYH6, COL14A1, and SPARCL1." (PMID 37421484, 2024).
childhood leukemia (1 paper, 2025). An acute or chronic leukemia that occurs during childhood. "We previously reported that SPARCL1 and CXADR are downregulated in cell lines that harbor translocations commonly associated with childhood leukemia; expression of these genes was de-repressed by inhibitors of repressive chromatin modifiers." (PMID 41497616, 2025).
colonic inflammation (1 paper, 2021). "Interestingly, SPARCL1, which has been shown to affect susceptibility to experimental colitis in mice was part of this group." (PMID 34409045, 2021). "Specific support for angiocrine functions in IBD was obtained from a recent report on an increased susceptibility for acute and chronic DSS-induced colonic inflammation in mice lacking the angiocrinely active SPARCL1 protein." (PMID 34409045, 2021).
congenital stromal corneal dystrophy (1 paper, 2024). Congenital stromal corneal dystrophy (CSCD) is an extremely rare form of stromal corneal dystrophy characterized by opaque flaky or feathery clouding of the corneal stroma, and moderate to severe visual loss. "Interestingly, SPARCL1 stimulates the expression of decorin, a known gene behind congenital stromal corneal dystrophy (CSCD), making this gene functionally a plausible cause for the new dystrophy." (PMID 39394466, 2024).